CDCP1 (CUB domain containing protein 1)
Diseases named in the same sentence as CDCP1 in open-access papers (continued):
Sharing a sentence is not in itself a finding about the gene and the disease.
pancreatic cancer (19 papers, 2014 to 2025). "CDCP1 has been identified on cells with phenotypic markers of mesenchymal stem cells or of neural progenitor cells, and its expression in pancreatic cancer tissue has been linked to maintenance of cancer stem-cell phenotypes (including gemcitabine resistance)." (PMID 26227951, 2015). "In this issue of the JCI, Lim, Zhou, and colleagues identify a tumor neoantigen generated upon cleavage of the CUB domain containing protein 1 (CDCP1) in pancreatic cancer." (PMID 35166242, 2022). "89Zirconium-labelled ch10D7 accumulates in CDCP1 expressing cells enabling detection of pancreatic cancer xenografts in mice by PET imaging." (PMID 36276654, 2022). "These Abs selectively target c-CDCP1–expressing pancreatic cancer cells and reduce tumor growth in vivo while substantially improving the safety profile compared with a pan-CDCP1–targeting approach." (PMID 35166238, 2022). "A second approach to targeting CDCP1 in pancreatic cancer involved the development of specific anti-CDCP1 CAR T cells." (PMID 35166242, 2022). "In this study, the authors used flow cytometric analysis of patient-derived xenografts to identify cell-surface targets enriched in pancreatic cancer cells, one of which was CDCP1 (referred to as CD318)." (PMID 35166242, 2022). "CUB-domain-containing protein 1 (CDCP1) is a transmembrane protein overexpressed in breast, colon, and pancreatic cancer." (PMID 35054034, 2022). "CDCP1, also known as CD318, gp140, SIMA135, and Trask, is a single-pass transmembrane glycoprotein that is overexpressed in several malignancies, including pancreatic cancer, where it correlates with worse prognosis." (PMID 35166242, 2022). "Several serine proteases, such as plasmin, matriptase, and uPA, have been shown to cleave CDCP1, are upregulated in solid tumors, such as pancreatic cancer, and are found in high levels in human clinical samples." (PMID 35166238, 2022). "The investigators generated CAR T cells specific for CDCP1 and showed efficacy in a transplantation model using human pancreatic cancer cell lines in immunodeficient mice." (PMID 35166242, 2022). "In pancreatic cancer, the extracellular domain of CDCP1 was previously utilized in a theranostic approach, using a radiolabeled antibody that resulted in a decrease in tumor growth." (PMID 35166242, 2022). "CDCP1 is a transmembrane glycosylated receptor protein known to be overexpressed in pancreatic cancers, including PDAC, and co-expression of CDCP1 and uPA has been found to be strongly predictive of poor clinical outcome in various cancer types." (PMID 35204653, 2022). "In a syngeneic pancreatic tumor model, these cleaved-specific Abs showed tumor-specific localization and antitumor activity with superior safety profiles compared with a pan-CDCP1 approach." (PMID 35166238, 2022). "The present study demonstrates the utility of a89Zr-labelled CDCP1-directed agent (10D7) for CRC and also extends the ovarian and pancreatic cancer studies by demonstrating the selectivity of 89Zr-10D7 for CDCP1 expressing tumors using unlabelled 10D7." (PMID 34621145, 2021). "We focused on this example and showed that recombinant antibodies to CDCP1 can be used to selectively deliver therapeutic cytotoxic payloads or recruit and activate T-cells to pancreatic cancer cells while sparing normal control cells." (PMID 29359686, 2018). "The EGF-EGFR axis promotes CDCP1 expression in ovarian cancer models, and bone morphogenetic protein 4 induces CDCP1 in pancreatic cancer cells." (PMID 29792166, 2018). "We further show in mouse xenograft models for pancreatic cancer that CDCP1 expression level is an abundant biomarker for RAS signaling through the MAPK signaling pathway." (PMID 29359686, 2018). "CDCP1 is reportedly expressed in normal epithelial cells, and overexpressed in epithelial tumor cells such as colon, breast, lung, renal and pancreatic cancers; expression of CDCP1 by bone marrow stromal cells has not been previously reported." (PMID 25275584, 2014).
pancreatic cancer (continued). "Deregulated CDCP1 expression has been detected in colon, lung, gastric, breast and pancreatic carcinomas, compared to normal tissues." (PMID 25301083, 2014). "Our initial observation that CDCP1 expression was driven by RAS dependent MAPK signaling in MCF10As was recapitulated in more than a dozen mutant RAS cancer cell lines as well as an in vivo model for pancreatic cancer." (PMID 29359686, 2018). "Furthermore, the evidence for this signaling axis is found in the TCGA for pancreatic cancer, where CDCP1 and all four identified integrins show significantly elevated mRNA levels in cancers with RAS mutations." (PMID 29359686, 2018). "As a final proof of concept application of our antibodies, we tested to see whether CDCP1 expression level could be used as an in vivo imaging marker for RAS signaling in a mouse xenograft model for pancreatic cancer." (PMID 29359686, 2018). "CDCP1 is a glycoprotein which is reportedly expressed in normal epithelial cells, and overexpressed in epithelial tumor cells such as colon, breast, lung, renal and pancreatic cancers and is said to regulate mechanisms related to inhibition of cell death." (PMID 29190740, 2017). "The PC-3 pancreatic cancer cell line was shown to express high levels of CDCP1 and SHP2." (PMID 25876044, 2015). "Furthermore, in pancreatic cancer cells, binding of the δ isoform of protein kinase C (PKCδ) to CDCP1 tyrosine 762 facilitated cell migration." (PMID 25301083, 2014). "Overexpression of CD318 (CDCP1) uniformly correlates with poor overall survival in lung, colon, ovarian, breast, renal, hepatocellular, acute myeloid leukemia and pancreatic cancers, partly due to its involvement in tumor metastasis formation via Src." (PMID 36275816, 2022). "Deregulated expression of the transmembrane glycoprotein CDCP1 (CUB domain-containing protein-1) has been detected in several cancers including colon, lung, gastric, breast, and pancreatic carcinomas." (PMID 25301083, 2014).
ovarian carcinoma (18 papers, 2015 to 2026). A malignant neoplasm originating from the surface ovarian epithelium. "CDCP1 has previously been implicated in tumor progression and metastasis across multiple malignancies, including colorectal, lung, and ovarian cancers." (PMID 41488282, 2026). "Tissue chips were prepared to analyze the relationship between different expression levels of CDCP1 and the prognosis of ovarian cancer patients." (PMID 37469398, 2023). "For validation, serum and ascites samples from patients with epithelial ovarian cancer (EOC) were collected, and their levels of CDCP1 was determined by enzyme-linked immunosorbent assay." (PMID 37469398, 2023). "Here we characterize two anti-CDCP1 antibodies, focusing on immuno-conjugates of one of these as a tool to detect and inhibit ovarian cancer." (PMID 32104500, 2020). "As a support, it has been shown that CDCP1 expression is regulated through ERK1/2 recruitment in ovarian cancer cells stimulated with EGF." (PMID 29792166, 2018). "Cell surface CDCP1 contributes to EGF/EGFR signaling-mediated migration in ovarian cancer with up-regulation of CDCP1 RNA and protein expression." (PMID 28537886, 2017). "For example, EGF signalling, via EGFR to RAS/RAF/MEK/ERK, simultaneously stimulates CDCP1 expression and promotes CDCP1-mediated in vitro migration of ovarian cancer cells." (PMID 26973855, 2016). "Therapeutic targeting of CDCP1 may improve outcomes for patients with this aggressive form of ovarian cancer." (PMID 40892739, 2025). "Targeting CDCP1 has proved effective in ovarian cancer models and may contribute to cell adhesion and cell-matrix association, which may be related to increased metabolic risks." (PMID 39314522, 2024). "Furthermore, cytotoxin-conjugated 10D7 was effective at inhibiting growth of CDCP1-expressing ovarian cancer cells in vitro and in vivo." (PMID 32104500, 2020). "Furthermore, using miR-654 as a therapeutic to target CDCP1 and treat ovarian cancers has been proposed." (PMID 32817447, 2020). "The elevated expression of CDCP1 on the surface of malignant cells has led to its investigation in pre-clinical models as a target for monoclonal antibodies (mAbs) that have therapeutic potential against prostate, breast and epithelial ovarian cancer (EOC) 9-12, 15, 20-24." (PMID 32104500, 2020). "According to previous studies, EGF reduces the palmitoylation of CUB domain-containing protein 1 (CDCP1) and inhibits the palmitoylation-dependent degradation of CDCP1 to promote its expression on the cell surface of ovarian cancer cells." (PMID 40733034, 2025). "For example, a cancer-promoting protein CDCP1 (CUB domain-containing protein 1) is degraded upon S-acylation, leading to a decrease of ovarian cancer cell migration." (PMID 28392791, 2017). "In ovarian cancer, activation of EGFR signaling prevents proteasomal degradation of CUB domain‐containing protein 1 (CDCP1) through CDCP1 palmitoylation at Cys689, Cys690, Cys772, and Cys780 and subsequent CDCP1 localization to the cell surface, where CDCP1 acts to enhance cell migration." (PMID 36018061, 2023).
triple-negative breast carcinoma (16 papers, 2016 to 2025). An invasive breast carcinoma which is negative for expression of estrogen receptor (ER), progesterone receptor (PR), and human epidermal growth factor receptor 2 (HER2). "Recently, IHC staining formalin-fixed and paraffin-embedded triple-negative breast cancers demonstrated that the expression of phosphorylated SFK at Y416 is closely associated with phosphorylated CDCP1 and PKCδ." (PMID 36862682, 2023). "CDCP1 is also proven to drive fatty acid oxidation and oxidative phosphorylation to promote metastasis of triple-negative breast cancer." (PMID 36862682, 2023). "Previous research has revealed that CDCP1 is a novel marker of triple-negative breast cancer and promotes tumor progression via reduction of lipid-droplet abundance and stimulation of fatty acid oxidation." (PMID 36090897, 2022). "CDCP1 upregulation upon the activation of the PDGFRβ/ERK axis was confirmed in two additionally triple negative breast cancer cell lines BT-549 and SUM149." (PMID 29792166, 2018). "CDCP1 disrupts lipid metabolism by reducing the abundance of lipid droplets and promoting fatty acid oxidation, which contributes to the migration and metastasis of triple-negative breast cancer." (PMID 40892739, 2025). "Thus, CDCP1 is a novel marker of the most aggressive human triple-negative breast cancers." (PMID 31824496, 2019). "In fact, in triple-negative breast cancer, ACSL3 interacts with the pro-metastatic protein CUB domain-containing protein 1 (CDCP1)." (PMID 31344914, 2019). "In contrast, studies with triple negative breast cancer cells showed that LD consumption through FAO and CUB-domain containing protein 1 (CDCP1) resulted in decreased lipid accumulation and increased metastatic potential." (PMID 30767150, 2019).
colorectal cancer (13 papers, 2014 to 2026). A primary or metastatic malignant neoplasm that affects the colon or rectum. "Taken together, the genetic (knockdown/overexpression), pharmacologic (BCI-121), and chromatin (ChIP) evidence demonstrate that CDCP1 is a direct chromatin target of SMYD3 in colorectal cancer cells." (PMID 41301830, 2025). "Treatment with 5-fuorouracil (5-FU) or oxaliplatin of KRAS mutant colorectal carcinomas in mice led to the enrichment of CUB-domain-containing protein 1 positive (CDCP1+) cells." (PMID 36497394, 2022). "In the current study, we observed that quiescent CUB-domain–containing protein 1 (CDCP1)+ CSCs are enriched after chemotherapy in mutant Kirsten rat sarcoma viral oncogene homolog (Kras) colorectal carcinomas (CRCs) and serve as a reservoir for recurrence." (PMID 31461438, 2019). "Recently, it has been shown that CDCP1 expression is required for the attachment of colorectal cancer cells to lung endothelial cells." (PMID 25469109, 2014). "We asked whether CDCP1 itself is sufficient to enhance malignant traits in colorectal cancer cells." (PMID 41301830, 2025). "This view has been challenged by a recent in vitro study with human colorectal cancer cells (CRC), in which both CD166/ALCAM and CD318/CDCP1 are highly expressed." (PMID 38139340, 2023). "We further confirmed these results in the HCT 116 colorectal cancer cell line, which expresses both SHP2 and CDCP1 (lane 1 middle panels)." (PMID 25876044, 2015). "It has recently been reported that the induction of CDCP1 phosphorylation triggered a set of discrete and specific signaling pathways, leading to the phosphorylation of SHP2 in HCT 116 colorectal cancer cells." (PMID 25876044, 2015).
lung adenocarcinoma (11 papers, 2015 to 2025). A carcinoma that arises from the lung and is characterized by the presence of malignant glandular epithelial cells. "In human studies, CUB domain containing protein 1 (CDCP1) expression has been found to strongly correlate with poor prognosis and relapse of lung adenocarcinoma patients." (PMID 39363014, 2024). "CDCP1, a cell surface glycoprotein for cell-cell interactions, promotes cancer metastasis and increase anchorage-free survival in lung adenocarcinoma." (PMID 28537886, 2017). "Moreover, a significant positive correlation of ADAM9 and CDCP1 expression was detected in lung adenocarcinoma patients from The Cancer Genome Atlas (TCGA) dataset (R = 0.377)." (PMID 28537886, 2017). "Although miR-1 was not significantly negatively correlated with CDCP1 in this small cohort, we observed a significant reverse correlation between miR-1 and CDCP1 in lung adenocarcinoma from the TCGA dataset." (PMID 28537886, 2017). "Consistent with the CDCP1 level, ectopic expression of CDCP1 lacking the 3′UTR increased cell migration and over-expression of miR-218 cannot inhibit the mobility of lung adenocarcinoma cells." (PMID 26553452, 2015). "The findings from the survival analysis in this study are not consistent with those in renal cell carcinoma and lung adenocarcinoma and may again verify the non-existence of the ADAM9/CDCP1/t-PA pathway in OSCC." (PMID 39441449, 2024).
colon carcinoma (10 papers, 2012 to 2025). "Researchers have observed that the expression of CST5 in human colon cancer cells is the opposite of CDCP1, significantly reducing the tumorigenic potential in immunodeficient mice." (PMID 39497803, 2024). "This patient-derived model retains the features of the original primary colon cancer displaying histology of a poorly differentiated adenocarcinoma and prominent cell surface localisation of CDCP1." (PMID 34621145, 2021). "Intestinal and colonic tumors also stained positive for migrating CSC markers CD110 and CDCP1 wherein, colonic tumors additionally exhibited stromal positivity." (PMID 31040926, 2019). "CDCP1 expression in colon cancer cell lines leads to modulation of cell:substratum adhesion and is required for maximal SW480 cell motility." (PMID 25301083, 2014). "The data described in this report has established a role for CDCP1 in colon cancer cell line adhesion and motility." (PMID 25301083, 2014). "Total cellular CDCP1 protein expression was examined in colon cancer cell lines by Western blotting." (PMID 25301083, 2014). "Treatment of the colon cancer cell line DLD-1 with an anti-CDCP1 antibody resulted in the stimulation of cell migration through filters." (PMID 25301083, 2014). "In this study, CDCP1 was shown to modulate cell-substratum adhesion and motility in colon cancer cell lines, with some variation depending on the colon cancer cell type." (PMID 25301083, 2014). "CDCP1 is highly expressed in lung and colon cancers, where it is phosphorylated by Src family kinases and involved in anchorage independence of cancer cells." (PMID 22433494, 2012). "Together with KAI1, CDCP1 has been reported to be a component of the TEM in colon cancer, but its function in this context has remained poorly characterized." (PMID 22390300, 2012). "The effect of CDCP1 on substratum adhesion of colon cancer cells was cell line-dependent." (PMID 25301083, 2014). "Both intestinal and colonic tumors also stained positive for migrating cancer stem cell markers CD110 and CDCP1 and Lgr5, respectively." (PMID 31040926, 2019). "CDCP1 and CD9 were co-expressed at the mRNA and protein level and we obtained evidence for the presence of a molecular complex of these proteins in SW480 colon cancer cells." (PMID 25301083, 2014). "CDCP1 and CD9 protein expression was measured in a series of colon cancer cell lines by flow cytometry and Western blotting." (PMID 25301083, 2014). "A positive correlation between CDCP1 and CD9 protein expression in colon cancer cell lines was demonstrated." (PMID 25301083, 2014). "A small subset of CD133-positive colon carcinoma cells additionally expressed CD24, CD44 or CDCP1, so that a correlation in antigen expression can be assumed." (PMID 22433494, 2012). "Our data revealed correlations in the expression of surface markers CD44 and CD24 as well as CD44 and CDCP1 and strongly suggest that CD133 is a stem cell marker within our colon carcinoma panel." (PMID 22433494, 2012). "Our study characterized a large panel of colon carcinoma cell lines and their corresponding xenografts, showing significantly reduced expression of the cell surface markers CD133, CD44, CD24, CDCP1 and CXCR4 in vivo." (PMID 22433494, 2012). "We characterized a panel of fourteen human colon carcinoma cell lines and their corresponding xenografts for the surface expression of potential stem cell markers CD133, CD24, CD44, CDCP1 and CXCR4." (PMID 22433494, 2012). "None of the colon cancer cell lines had significantly higher CDCP1 expression than HaCaT." (PMID 25301083, 2014). "Because CDCP1 is reported to localize in the TEM of colon cancer by proteomic analysis, we could not exclude a possible interaction between KAI1 and CDCP1." (PMID 22390300, 2012).
colon carcinoma (continued). "CUB domain-containing protein 1 (CDCP1) may be involved in cell adhesion or extracellular matrix interaction, and the expression of CDCP1 has been shown to correlate with the metastasis of carcinoma cells, such as in cancers of the colon, lung, breast, and pancreas." (PMID 29402311, 2018). "The expression of CDCP1 and CD9 proteins has not been extensively characterised in colon cancer cell lines." (PMID 25301083, 2014). "Thus, although over expression of CDCP1 in Colo320 decreased the binding to Matrigel, a reduction in endogenous CDCP1 expresion did not alter the binding to Matrigel in the SW480 background, suggesting that the effect of CDCP1 on ECM adhesion may be colon cancer cell line-specific." (PMID 25301083, 2014).
COVID-19 (9 papers, 2022 to 2025). A disease caused by infection with severe acute respiratory syndrome coronavirus 2. "Meanwhile, five proteins exert protective effects against hospitalization and progression to critical COVID-19 (OR: 0.85~0.95), including CXCL11, CDCP1, CCL4/MIP, IFNG, and LIFR." (PMID 38455043, 2024). "We identified that only three proteins, namely TNF, SLAMF1, and CDCP1, were differentially abundant in critically ill COVID-19 patients compared to those with non-critical illness presentation." (PMID 40475767, 2025).